LOX (lysyl oxidase)
Diseases named in the same sentence as LOX in open-access papers (continued):
Sharing a sentence is not in itself a finding about the gene and the disease.
emphysema (7 papers, 2006 to 2026). "Although impaired cross linking of matrix protein as a consequence of LOX inhibition provides a rather intuitive explanation for emphysema development in copper-deficient animals, the published data regarding LOX activity dependent emphysema are controversial." (PMID 22276220, 2012). "Animals fed a Cu-deficient diet also develop emphysema, as Cu deficiency prevents LOX activation." (PMID 38883186, 2024). "In experimental emphysema, impairment of LOX production exacerbates alveolar destruction and emphysema." (PMID 27761886, 2016). "The Cu-dependent coregulation of VEGF and LOX plays roles in angiogenesis and in emphysema." (PMID 32708046, 2020). "Fifteen genes were thus found to be upregulated in fibroblasts of emphysema, among them IGFBP-rP1 (4.9-fold), LOX (3.3-fold), LOXL2 (3.9-fold) and TIMP3 (3.0-fold), whereas 121 genes were downregulated, among them CDK4 (6.3-fold), FOSL1 (4.8-fold), OAZ1 (6.7-fold) and IGFBP-5 (5.3-fold)." (PMID 16504044, 2006). "VEGF and LOX are also coregulated by the Cu-dependent activation of HIF-1α, the absence of which contributes to emphysema (shown in rat lungs) and involves histone deacetylase HDAC2-mediated expression of HIF-1α, VEGF." (PMID 32708046, 2020).
endothelial dysfunction (7 papers, 2018 to 2024). In vascular diseases, endothelial dysfunction is a systemic pathological state of the endothelium (the inner lining of blood vessels) and can be broadly defined as an imbalance between vasodilating and vasoconstricting substances produced by (or acting on) the endothelium. "Reduced LOX expression was associated with endothelial dysfunction, fatty streak formation, and rupture of the atherosclerotic plaque, whereas increased LOX expression was positively correlated with vascular calcification as well as vascular stiffness." (PMID 36292250, 2022). "Downregulated LOX has been associated with endothelial dysfunction and upregulated LOX has been associated with induced VSMC migration, and solubilization of ECM components." (PMID 36358914, 2022). "Taken together these results indicate that LOX dysregulation underlies endothelial dysfunction elicited by cardiovascular risk factors." (PMID 31615160, 2019). "Hyperhomocystinemia, an atherosclerotic risk factor that induces endothelial dysfunction and alters the elastic properties of the vascular wall, also inhibits LOX activity and negatively regulates endothelial LOX expression at the transcriptional level." (PMID 31615160, 2019). "LOX is highly expressed in the endothelium of healthy arteries, and multiple evidence associates LOX downregulation with endothelial dysfunction." (PMID 31615160, 2019). "In conclusion, we successfully identified three “real” hub genes (VEGFA, CDC25A, and LOX), and six crucial miRNAs (hsa-mir-24-3p, hsa-mir-124-3p, hsa-mir-195-5p, hsa-mir-146a-5p, hsa-mir-155-5p, and hsa-mir-23b-3p) associated with endothelial dysfunction in HPH based on bioinformatic analysis." (PMID 36483920, 2022). "The alteration of LOX and fibulin fits well with the concept that COVID-19 patients experience endothelial dysfunction." (PMID 35743918, 2022). "Different mechanisms link LOX virtually to all stages of the atherosclerotic process, from endothelial dysfunction and plaque progression in the early stages, to calcification and rupture of advanced and complicated plaques." (PMID 31615160, 2019). "Although inducers of endothelial dysfunction commonly downregulate LOX, in human endothelial cells LOX is upregulated by advanced glycation end products (AGEs) via RAGE/MAPK signaling and NF-κΒ and AP-1, thereby impairing endothelial homeostasis." (PMID 31615160, 2019). "Lysyl oxidase (LOX) plays an important role in extracellular matrix (ECM) stabilization and may be related to endothelial dysfunction induced by atherosclerotic risk factors." (PMID 38473850, 2024). "In the vascular smooth muscle cells, increased SSAO activity elevates reactive oxygen species (ROS) and induces VSMCs death; increased LOX induces chemotaxis through hydrogen peroxide dependent mechanisms; and decreased LOX contributes to endothelial dysfunction." (PMID 36358914, 2022). "Indeed, endothelial LOX expression is strongly inhibited by different conditions, which trigger endothelial dysfunction including high levels of low-density lipoproteins (LDL), hyperhomocysteinemia, and pro-inflammatory cytokines." (PMID 31615160, 2019). "Inhibition of LOX activity could results in endothelial dysfunction and plaque progression." (PMID 29915377, 2018).
prostate tumor (7 papers, 2015 to 2025). "High LOX mRNA expression is associated with high-grade prostate tumors and tumor recurrence and has been shown to correlate with GS." (PMID 26501565, 2015). "Inversely, LOX mRNA expression was decreased in metastatic compared to primary prostate tumors and low levels of LOX expression have also been reported in high-grade tumors, suggesting loss of LOX expression during prostate tumor progression." (PMID 26501565, 2015). "Because CAF also regulate the migration ability of prostate tumor epithelium, we next assessed the potential paracrine role of LOX/LOXL2 secreted by CAF." (PMID 31061140, 2019). "Taken together, these results suggest that some factor or factors in the prostate microenvironment up-regulate the expression of LOX enzymes both in prostate tumour tissue and in the surrounding normal prostate tissue." (PMID 26804196, 2016). "This is supported by our finding that orthotopic rat prostate tumor cells implanted to the prostate of rats resulted in increased expression of LOX mRNA in TINT compared to tumor-free control tissue." (PMID 26501565, 2015). "For example, the overexpression of PLOD2 and LOX has been correlated with poor outcomes in multiple cancers, and their detection in prostate tumors may help stratify patients who would benefit from more aggressive treatments or ECM-targeting therapies." (PMID 40943497, 2025). "However, the LOX mRNA levels were significantly higher in CRPC bone metastases compared to the levels in the primary prostate tumors." (PMID 26501565, 2015). "This study suggests that high LOX synthesis in tumor epithelial and in the epithelial cells in the tumor-bearing organ may stimulate prostate tumor growth and spread." (PMID 26501565, 2015). "Furthermore, and in line with some previous reports we show that LOX-IR in prostate tumor epithelium was correlated to several clinical characteristics related to tumor aggressiveness such as GS, tumor stage, microvessel density, tumor proliferation and metastases." (PMID 26501565, 2015). "Combined, these data indicate that LOX/LOXL2 production by prostate CAF produces a highly aligned ECM that can potentiate the migration of CAF themselves, as well as neighboring prostate tumor cells." (PMID 31061140, 2019). "LOX immunoreactivity was scored in prostate tumor epithelium, tumor stroma and in the tumor-adjacent non-malignant prostate epithelium and stroma." (PMID 26501565, 2015). "The hypothesis that the non-malignant parts of the tumor-bearing prostate could be a significant contributor is supported by our observation that LOX mRNA levels are similar in human prostate tumors and in adjacent non-malignant prostate tissue." (PMID 26501565, 2015). "Further studies are needed to examine how prostate tumors may stimulate non-malignant prostate cells to increase their LOX expression." (PMID 26501565, 2015).
thoracic aortic aneurysm (7 papers, 2013 to 2022). An aneurysm formed in the wall of the proximal portion of the descending aorta proceeding from the arch of the aorta. "LOX is encoded by the LOX gene on chromosome 5q, and defects in this gene have been linked with predisposition to thoracic aortic aneurysms and OSMF." (PMID 33143101, 2020). "The dominant LOX variation contributes to familial thoracic aortic aneurysm." (PMID 35743192, 2022). "In agreement with our findings, a recent study reported that amlodipine profoundly reduced incidence of abdominal and thoracic aortic aneurysms in normocholesterolemic mice co-administered either AngII or deoxycorticosterone acetate-salt with a lysyl oxidase inhibitor, beta-aminopropionitrile." (PMID 24244746, 2013).
asthma (6 papers, 2019 to 2026). "Agents that inhibit the LOX‐mediated signaling pathway have since been used to treat inflammatory diseases such as asthma and arthritis." (PMID 41573111, 2026). "Drugs that modulate LOX have also been shown to have a better rehabilitative intervention effect for asthma, and ALOX 5 or LT receptor antagonists have been developed for the treatment of asthma." (PMID 40605076, 2025). "Identifying the significant role 5-LOX plays in mediating asthma poses an interesting question about the role and therapeutic potential of other LOX enzymes, particularly 12/15-LOX, in asthma." (PMID 37253655, 2023). "Regarding LOX enzymes, research shows that 5-LOX activity has a significant role in promoting inflammation in asthma." (PMID 37253655, 2023). "Similarly, in asthma, it has been shown that the homeostatic balance between the COX and LOX pathways metabolizing ARA are altered due to damaged epithelium in asthmatic airways." (PMID 35095496, 2021). "A prior murine study showed that administration of the lysyl oxidase inhibitor β-aminoproprionitrile (BAPN) to TGF-β1-treated mice blocked airway collagen deposition, thereby showing the importance of this enzyme in ECM deposition, a fundamental component of airway remodeling in asthma." (PMID 38057814, 2023).
glaucoma (6 papers, 2020 to 2024). Increased pressure in the eyeball due to obstruction of the outflow of aqueous humor. "Further, LOX, LOXLs and TGM2 do have their place in glaucoma; single-nucleotide polymorphism in LOXL1 has been implicated in exfoliation glaucoma." (PMID 32973273, 2020). "Some of these autoantibodies react with proteins which have previously been associated with glaucoma, such as LOX and TMEM9B, as well as proteins which have little or no previous association with the disease, such as CDH5 and FUT2." (PMID 38287276, 2024). "The investigation of glaucoma-related cross-linking proteins, such as lysyl oxidase (LOX)/lysyl oxidase-like 1 (LOXL1), tissue trans-glutaminase (TG2), and advanced glycation end products, will allow corneal gene therapy to be further developed into a promising treatment of glaucoma." (PMID 35652098, 2022).
Hyperglycemia (6 papers, 2014 to 2025). An increased concentration of glucose in the blood. "Building on evidence of hyperglycemia-triggered endothelial LOX/LOXL2 overexpression, we provide causal evidence that GEnC-secreted LOX/LOXL2 enzymes directly induce mesangial cell dysregulation, driving oxidative stress, fibrosis, and collagen synthesis." (PMID 41355449, 2025). "It was postulated that a hyperglycemia-induced vitamin B6 deficiency caused the down-regulation of lysyl oxidase (LOX) and an eventual reduction in immature crosslinks." (PMID 33139851, 2020). "Recent studies have demonstrated that in diabetic mouse models, hyperglycemia upregulates the expression of lysyl oxidase (LOX) by activating the TGF-β signaling pathway." (PMID 41180198, 2025). "Hyperglycemia was shown to influence corneal biomechanical properties by inducing stromal collagen CXL through glycosylation and lysyl oxidase (LOX) enzymatic activity." (PMID 25215226, 2014).
metastatic cancer (6 papers, 2014 to 2023). A carcinoma which has spread from the original site of growth to another anatomic site. "It is noteworthy that very significant progress in developing small molecule pan-lysyl oxidase isoform inhibitors and isoform-specific LOX inhibitors is a promising current avenue of ongoing research that seems likely to lead to new therapies for fibrosis and possibly metastatic cancer." (PMID 29082249, 2017). "Furthermore, inhibition of LOX has been proposed to treat hypertensive and fibrotic disorders and metastatic cancers." (PMID 24614111, 2014). "The results also showed a tendency towards upregulation for LOX when non-metastatic were compared to metastatic cancer samples, with the p value very close to significant (p = 0.058)." (PMID 32013938, 2020).
non-small cell lung carcinoma (6 papers, 2018 to 2026). A group of at least three distinct histological types of lung cancer, including non-small cell squamous cell carcinoma, adenocarcinoma, and large cell carcinoma. "Of note, LOX was recently found to be a poor prognostic indicator in various solid tumors such as non-small cell lung cancer, nasopharyngeal carcinoma and prostate cancer." (PMID 31439905, 2019). "RNAi experiments revealed that downregulation of LOX after siRNA treatment inhibited hypoxia-induced migration and invasion in non-small cell lung cancer." (PMID 31061665, 2019). "Similarly, the EGFR/MAPK/LOX axis has been shown to promote the metastatic spread of non-small cell lung cancer." (PMID 41399365, 2026). "Moreover, we confirmed that LOX expression is regulated by the activation of epidermal growth factor receptor (EGFR) via the PI3K/AKT, MEK/ERK, and SAPK/JNK signaling pathways in non-small cell lung cancer (NSCLC)." (PMID 29472856, 2018).
pancreatic ductal adenocarcinoma (6 papers, 2016 to 2025). An infiltrating adenocarcinoma that arises from the epithelial cells of the pancreas. "A recent study demonstrated that LOX inhibition reduces stromal matrix deposition, thereby enhancing chemotherapy efficacy in pancreatic ductal adenocarcinoma." (PMID 40396123, 2025). "Our findings present the rationale for progression of a pan-lysyl oxidase inhibitor aimed at eliciting a reduction in stromal matrix to potentiate chemotherapy in pancreatic ductal adenocarcinoma." (PMID 37640930, 2023). "Mechanical properties of the mouse pancreatic ductal adenocarcinoma KPC tumor model and effects of LOX inhibition." (PMID 34106045, 2021). "The activity of lysyl oxidase (e.g., LOX and LOXL2) also, correlates with oncogenic stress response and tumorigenesis in pancreatic ductal adenocarcinoma." (PMID 27285767, 2016).
renal cell carcinoma (6 papers, 2014 to 2024). "VEGFA, KDR, LYN, CD3E and LOX are among those factors that are not identified by DIAMOnD but have a renal cell carcinoma associated literature support." (PMID 29861861, 2018). "In renal cell carcinoma cell lines miR-145-5p is dysregulated and several targets, including e2F-associated phosphoprotein (EAPP), Heparan Sulfate 6-O-Sulfotransferase 2 (HS6ST2), Lysyl Oxidase (LOX), Transforming Growth Factor beta-2 (TGFB2) and Vaccinia-related Kinase 2 (VRK2), were confirmed." (PMID 30102719, 2018). "LOX has a significant effect on ECM remodeling in the lungs and promotes lung metastasis and correlates with increased staging in renal cell carcinoma." (PMID 34930321, 2021). "Recently, lysyl oxidase (LOX) has been identified as an important regulator of hypoxia-induced tumor progression via an HIF-1α-dependent mechanism in a variety of human cancers including breast, colon, head and neck, ovarian, prostate and renal cell carcinomas." (PMID 25174950, 2014).
systemic sclerosis (6 papers, 2021 to 2025). A chronic disorder, possibly autoimmune, marked by excessive production of collagen which results in hardening and thickening of body tissues. "In the edematous phase of systemic scleroderma, LOX staining was increased in the intra- and extracellular dermis, indicating that LOX is highly expressed in skin lesions where fibrosis occurs." (PMID 39859514, 2025). "LOX expression and activity are increased in both animal models and patient samples of ALS, and LOX, LOXL2 and LOXL4 are elevated in the fibroblasts and serums of patients with systemic sclerosis." (PMID 35205728, 2022).
astrocytomas (5 papers, 2015 to 2024). "Our group has previously reported a correlation between increased LOX expression and higher malignancy grade in human astrocytomas, and also a correlation of LOX expression with IDH1 mutation status." (PMID 36076905, 2022). "In a previous study by our group, a correlation of LOX expression level with IDH1 mutation status was found in diffusely infiltrative astrocytomas (grades 2 to 4)." (PMID 36076905, 2022). "Recent reports indicate that the cellular localization of LOX protein in tissue of astrocytomas is associated with the malignancy of the tumor." (PMID 27336447, 2016). "In contrast, stepwise upregulation of HIF1A observed in our cases of diffusely infiltrative astrocytomas associated with high expression of LOX and BMP1 suggest progressive activation of both angiogenic and invasive pathways." (PMID 25790191, 2015). "Besides being associated with tumor aggressiveness, LOX was lower in mIDH1 grade II and IV astrocytomas compared to wIDH1." (PMID 28234925, 2017). "Taken together, these results corroborate the role of LOX in the migration, invasion and angiogenesis of astrocytomas." (PMID 25790191, 2015). "Although it is known that LOX is involved in invasion, proliferation and tumor migration in other types of tumors, studies of LOX in astrocytomas of different grades are scarce." (PMID 25790191, 2015). "In summary, our results confirmed that LOX plays an important role in migration and angiogenesis in diffusively infiltrative astrocytomas, especially GBMs." (PMID 25790191, 2015). "Secreted LOX is responsible for the invasive properties of hypoxic cancer cells, including astrocytomas, through the activation of focal adhesion kinase (FAK)/paxillin." (PMID 25790191, 2015). "LOX is the most extensively studied member of this family and, in a previous study by our group, a progressive increase in LOX expression according to malignancy was observed in human astrocytomas." (PMID 36076905, 2022). "Using an antibody against the C-terminus of LOX that detects only the 50 kDa pro-LOX or the processed active 32 kDa LOX, we have unequivocally detected a high level of LOX nuclear staining, particularly in the most malignant astrocytomas (grades III and IV)." (PMID 25790191, 2015). "Survival analysis demonstrated that LOX and HIF1 were connected to astrocytoma prognosis, and functional investigations demonstrated that LOX might contribute to the initiation and progression of astrocytoma by regulating tumor cell proliferation and angiogenesis." (PMID 38339384, 2024). "The results demonstrate that increased expression and activity of LOX, BMP1 and HIF1A were positively correlated with the malignant grade of astrocytomas." (PMID 25790191, 2015). "In the present study, we investigated the expression of LOX, BMP1 and HIF1A in astrocytomas of different malignant grades." (PMID 25790191, 2015). "The progressive gene expression connectivity among LOX, LOXL1, and LOXL3 and matrisome-related genes from LGG-IDHmut, LGG-IDHwt, and through to GBM, reinforce the impact of ECM components contributing for matrix stiffness on the malignant progression and prognosis of astrocytoma." (PMID 36076905, 2022). "Gene expression analysis by quantitative real-time PCR (RT-qPCR) for LOX, LOXL1, LOXL2, LOXL3, and LOXL4 showed increased expression levels in astrocytoma samples compared to non-neoplastic (NN) samples." (PMID 36076905, 2022). "LOX, BMP1 and HIF1A expression analysis by qRT-PCR showed great variability in astrocytomas of all malignant grades when compared to non-neoplastic samples." (PMID 25790191, 2015). "The purpose of our study was to characterize LOX, BMP1 and HIF1A expression by real-time PCR in astrocytomas with WHO grades I to IV compared to non-neoplastic brain tissue." (PMID 25790191, 2015).